IL1A (interleukin 1 alpha)
Diseases named in the same sentence as IL1A in open-access papers (continued):
Sharing a sentence is not in itself a finding about the gene and the disease.
glioma (16 papers, 2014 to 2025). A benign or malignant brain and spinal cord tumor that arises from glial cells (astrocytes, oligodendrocytes, ependymal cells). "So we also substantiated a crucially positive correlation of the risk score with IL-1α, IL-1β, IL-6, IL-8, and IL-18 expression levels in patients with glioma." (PMID 34114970, 2021). "Ca2+‐ATPase activity in membranes from human glioblastoma (U‐251, U‐138) and rat glioma (C6) cell lines, untreated (Control) and treated with cytokines (3 ng·mL−1 of IL‐1α, 30 ng·mL−1 of TNF‐α, and 400 ng·mL−1 of C1q), or with 5 μm Aβ1‐42 or 10 nm tau." (PMID 40325855, 2025). "The release of cytokines IL-1α and IL-8 in cell conditioned media from glioma cells exposed to 30, 60 and 90 μM S4 were dramatically increased." (PMID 37386564, 2023). "IL1A, interleukin 1α, is a ubiquitous and pivotal pro-inflammatory cytokine, which modulates the glioma microenvironment and increases tumor invasion, migration, and angiogenesis." (PMID 37891828, 2023). "Among these six genes, ANG, IL1A, LOXL1, LOXL2, and STEAP3 played risk roles in the survival of glioma patients (HR > 1), while F5 was a potential protective factor (HR < 1)." (PMID 37891828, 2023). "Compared with HA 1800 and HMC3 cell lines, the expression levels of CASP4, CASP9 and GSDMC showed an overall upward trend, and the IL1A level showed an overall downward trend in glioma cell lines." (PMID 35547808, 2022). "Our studies of human and mouse astrocytes and glioma cells demonstrate that IL-1α mRNA and protein are co-induced and co-regulated with IL-1β, as in myeloid cells (data not shown)." (PMID 25054228, 2014). "Finally, combined with Multivariate Cox regression analyses, four PRGs (CASP4, CASP9, GSDMC, IL1A) were identified as prognostic biomarkers for glioma patients." (PMID 35547808, 2022). "Various inflammatory cytokines, including TNF, CSF2, IL1A, IL17A, IL6, and IFNG, were predictively inhibited in glioma samples exhibiting high CSMD1 expression." (PMID 38561856, 2024). "Our study showed that IL1A is negatively correlated with OS and positively correlated with WHO classification of glioma patients." (PMID 35547808, 2022). "The remaining genes (IL-1α, CXCL7, IL-18RAP, CCL3) have not been well-studied in glioma, with the exception of CCL3, which is shown to improve the response to dendritic cell vaccines of patients with GBM." (PMID 31475119, 2019).
type 2 diabetes (16 papers, 2010 to 2025). "Similarly, CXCL10, IL-22, IL-21, and IL-1α were negatively associated with the need for mechanical ventilation and coma duration." (PMID 41219650, 2025). "A recent study, described that almost 20 circulating cytokines such as TNFα, IL-1a, IL-1b, GM-CSF, IL-10, IL-12, etc., are elevated in plasma of type 2 diabetic patients." (PMID 34202017, 2021). "This is probably due to increased levels of inflammatory cytokines TNFα and IL-1α in Type 2 diabetes." (PMID 27649540, 2016). "Overall these data highlight that the simultaneous presence of CHC and type 2 diabetes induces an evident increase of the following proinflammatory cytokines: IL-1α, IL-2R, IL-12, IL-18, CXCL9, MIF and HGF." (PMID 22745767, 2012). "IL-1α is a critical proinflammatory cytokine involved in cartilage catabolism and the pathogenesis of type 2 diabetes." (PMID 20604941, 2010). "Il1α, together with Il1β, belongs to the interleukin-1 family, which has been much more studied in the context of metabolic diseases, and its inhibition is one of the pharmacological strategies being tested as a treatment for type 2 diabetes." (PMID 40426854, 2025). "The underlying mechanism may be related to inflammatory mediators including IL-6, IL-1α, and TNF-α, which not only promote epithelial–mesenchymal transition through activation of the Janus kinase/signal transducer and activator of trans-ions pathway but also increase the risk of type 2 diabetes." (PMID 34956904, 2021). "The levels of MIF, insulin, ghrelin, leptin, glucagon, resistin and adipsin are similar in type 2 diabetes and CHD patients whereas IL-1α, IL-2R, IL-12, IL-18, HGF, and PAI-1 are higher in CHD patients than in type 2 diabetes patients (with p-value <0.01)." (PMID 22745767, 2012).
endotoxemia (15 papers, 2015 to 2024). "Neonatal pulmonary IL-1α expression was significantly increased compared to adults in response to both sublethal and lethal endotoxemia." (PMID 31354715, 2019). "Caspase-11 activation and subsequent GSDMD cleavage lead to the release of IL-1α in endotoxemia and bacterial sepsis." (PMID 31492850, 2019). "Our data show that IL-1α expression is robustly and uniquely upregulated during the saccular stage of pulmonary development in response to endotoxemia." (PMID 31354715, 2019). "We have demonstrated that sustained pulmonary NFκB signaling leads to developmentally regulated pulmonary IL-1α expression in neonatal endotoxemia." (PMID 31354715, 2019). "Next, we evaluated pulmonary IL-1α expression over a time course in neonatal (P0) and adult mice exposed to lethal (50 mg/kg) or sublethal (5 mg/kg) endotoxemia." (PMID 31354715, 2019). "We found that endotoxemia induced IL-1α expression during the saccular stage of neonatal lung development and was not present in the other neonatal organs or the adult lung." (PMID 31354715, 2019). "We found that with endotoxemia, both p50 and p65 were present at the IL-1α promoter in the neonatal lung at 5 h of exposure." (PMID 31354715, 2019). "Outcome of endotoxemia was unaffected in IL-1α TM mice, consistent with previous findings in Il1r1-/- mice." (PMID 30926232, 2019). "Consistent with previous works, genetic deletion of Caspase-11 blocked the release of IL-1α and IL-1β in endotoxemia." (PMID 30587103, 2018). "CGA-JK3 suppressed mRNA and protein levels of TNF-α or IL-1α in LPS-activated macrophages, which was consistent with the in vivo effects in endotoxemia- or ALF-induced mice." (PMID 28145460, 2017). "In accordance, VDR KO mice have shown to be more susceptible to LPS-induced endotoxemia, have higher expressions of inflammatory cytokines (e.g., TNF-α, IL-1a, IL-1β, IL-10, IL-21, and IFN-γ), and experience more weight loss, bleeding, ulceration, septic shock, and death compared to wild-type mice." (PMID 28066436, 2016). "In mice, the loss of IL-1α, but not IL-1β, results in decreased survival rates in response to lethal endotoxemia, and impaired immune function during infection." (PMID 25528766, 2015). "Moreover, we analyzed pro-inflammatory cytokines and chemokines in the plasma of Cdk5LysMCre and Cdk5flox mice during LPS-induced endotoxemia, since in vitro studies using c-Maf knockout macrophages showed elevated levels of Ccl5 and Il-1a in addition to Il-10." (PMID 34502552, 2021). "However, future detailed analyses of CCL3, IL-16, and IL-1α in this setting might provide additional insights into potential mechanisms mediating the observed protection against endotoxemia." (PMID 29928698, 2018). "However, deletion of GBP2 only slightly inhibited the release of IL-1α and IL-1β in endotoxemia." (PMID 30587103, 2018). "Notably, deletion of GBPs markedly reduced the release of IL-1α and IL-1β in endotoxemia." (PMID 30587103, 2018). "We have previously demonstrated, via measurements of splenic and whole blood levels of TNFα and splenic levels of IL-1α, that splenic pFUS modulates the systemic signaling of CAP and NF-KB in a rat model of endotoxemia." (PMID 36478877, 2022). "During the development of endotoxemia, LPSs bind to toll-like receptor 4 (TLR4) and increase the concentration of inflammatory markers such as IL-1α, IL-6, INF-γ, and TNF-α, and consequently systemic chronic intestinal inflammation may develop." (PMID 39193369, 2024). "There was no significant change in pulmonary IL-1α expression in endotoxemia-exposed pseudoglandular/canalicular (e15) lung." (PMID 31354715, 2019). "Deletion of IFN-α/βR, the receptor for type 1 IFN, but not Rip3, significantly inhibited the release of IL-1α and IL-1β in endotoxemia." (PMID 30587103, 2018).
endotoxemia (continued). "Importantly, IL-1α expression remained significantly elevated in the neonatal lung 24 h following the one-time exposure to sublethal endotoxemia on the day of birth while IL-1α expression was not significantly elevated at 24 h in the lungs of adult mice." (PMID 31354715, 2019).
hepatocellular carcinoma (15 papers, 2012 to 2024). A malignant tumor that arises from hepatocytes. "An in vivo and in vitro investigation on hepatocellular carcinoma (HCC) illustrated that tumor-derived IL-1A promoted tumor growth by increasing tumoral infiltration of myeloid-derived suppressor cells (MDSCs), which suppressed T and NK cell activation." (PMID 36071472, 2022). "Its anti‐tumour properties have also been elucidated in a study on the human hepatoma cell line, HepG2, where it induced apoptosis by increasing the levels of IL‐1α and TNF‐α in those cells." (PMID 35838746, 2022). "Interference with IL-1α signaling or ablation of IL-1R1 inhibited hepatocellular carcinoma (HCC) development." (PMID 28152513, 2017). "Our in vitro studies confirmed that IL‐1α/β treatment significantly reduces PGC‐1α and FXR‐α mRNA levels in the human hepatoma cell line HepG2, in human and mouse primary hepatocytes, as previously reported." (PMID 36101976, 2022). "The response to lenvatinib revealed two genes unique to Huh7 cells, 14 unique to HepG2 cells, and two genes (IL1A and TLR4) upregulated in both human hepatoma cell lines." (PMID 32397371, 2020). "In addition, serum IL-1α was increased in patients with chronic hepatitis C (HCV), cirrhosis, and hepatocellular carcinoma (HCC) compared with healthy controls." (PMID 36117587, 2022).
prostate carcinoma (15 papers, 2008 to 2025). A carcinoma that arises from epithelial cells of the prostate gland. "A pro-inflammatory cytokine, IL-1α, has been implicated in angiogenesis and invasiveness through evidence in mouse models and is increased in the serum of prostate cancer patients when compared to normal donors." (PMID 33034643, 2020). "The authors conclude that the cytokines IL-1α, IL-1β, IL-6, and IL-8 have a significant role in prostate cancer development." (PMID 37048115, 2023). "IL-1a and IL-1ß activate NF-kB to promote tumor cell survival through anti-apoptotic signaling pathway in prostate cancer." (PMID 36733309, 2023). "MDSCs infiltrate into PTEN null prostate cancer cells and induce the stemness of prostate cancer cells via producing IL-1Ra and blocking the IL-1α/IL-1R axis." (PMID 35154134, 2022). "Taken together, simulated μg induced 3D growth of PC-3 cancer cells combined with a differential expression of the cytokines IL-1α, IL-1β, IL-6 and IL-8, supporting their involvement in growth and progression of prostate cancer cells." (PMID 35252204, 2022). "Our studies indicate that IL-1α promotes the transition from indolent to progressing disease and therefore provides a potential new therapeutic target for treatment of prostate cancer." (PMID 29502208, 2018). "The IL-1α pathway target CXCL8, which is associated with prostate cancer disease progression and reduced survival, was up-regulated in myeloid-driven tumor cells." (PMID 29502208, 2018). "The IL-1α pathway target CXCL8 (IL-8) is associated with disease progression and overall survival in human prostate cancer." (PMID 29502208, 2018). "Reports in prostate cancer models suggest that reduction or inhibition of p27 blocks induction of senescence, and investigations into the precise roles of p27 and IL1α in senescence in multiple cell types are ongoing." (PMID 24244740, 2013). "In this case-control study, we investigated the association between polymorphisms in cytokine/chemokine genes (TNF-A -308 G/A, RANTES-403 G/A, IL-1A -889 C/T and MCP-1 2518 G/A) and prostate cancer risk." (PMID 19099590, 2008). "The objective of this study was to assess the influence of genetic polymorphism of RANTES, MCP-1, IL-1A and TNF-A on the risk of prostate cancer." (PMID 19099590, 2008). "IL-1α and IL-6 were up-regulated in prostate cancer samples." (PMID 26683658, 2015). "In prostate cancer, a high lipid diet may accelerate tumor cell proliferation by increasing levels of insulin-like growth factor 1, IL-1α, IL-1β, IL -6, or TNF-α or through activation of signaling pathways such as MCP-1/CCR2 (monocyte chemoattractant protein-1/C-C Motif Chemokine Receptor 2)." (PMID 38028534, 2023). "Finally, no overall association was found between prostate cancer risk and IL1-A or MCP-1 polymorphisms." (PMID 19099590, 2008). "In their pilot study with 15 prostate cancer patients, they evaluated the effects of a 24-week HOET on IL-1α, IL-5, IL-6, IL-12, TNF-α, and IFN-γ." (PMID 40498221, 2025).
systemic sclerosis (15 papers, 2012 to 2024). A chronic disorder, possibly autoimmune, marked by excessive production of collagen which results in hardening and thickening of body tissues. "Kawaguchi and colleagues examined rs17561 in the context of systemic sclerosis, where they reported increased calpain processing of pro‐IL‐1α in fibroblast lysates derived from minor allele homozygotes also suffering from systemic sclerosis." (PMID 36175368, 2023). "The rs1800587 C/T SNP of IL1A gene has been related to susceptibility to systemic sclerosis in a Slovak Caucasian population, Graves’ ophthalmopathy in an Iranian population, and Graves’ disease in a Tunisian population." (PMID 29879187, 2018). "In systemic sclerosis within the fibroblasts play a central role in the pathophysiology, the interplay between pathological keratinocytes and the underlying fibroblasts involving IL-1α was described to be important in the fibrotic process." (PMID 36268013, 2022). "However, the IL1A rs1800587 and rs17561 SNPs were also reported to be associated with the risk of systemic sclerosis in a Japanese population." (PMID 29879187, 2018). "The role of RAGE in skin remodeling and systemic sclerosis is already a defined process, worth mentioning also in this review: among other alarmins such as IL-33 and IL-1α, HMGB1 seems to play a major role as a ligand for the RAGE receptor." (PMID 33435332, 2021). "In an Iranian study, the authors reported that some haplotypes of SNPs IL-1A rs1800587, IL-1B rs1143634 and IL1R1 rs2234650 were associated with systemic sclerosis." (PMID 32252823, 2020). "IL-1α regulates the differentiation of fibroblasts into myofibroblasts and influences the longevity of myofibroblasts, both of which are pivotal processes in systemic sclerosis (SSc)." (PMID 39334819, 2024). "Increased concentrations of interleukin (IL)-1α have been recently described in tissues of patients with systemic sclerosis (SSc) suggesting that IL-1α inhibition may be a target for treatment." (PMID 37680472, 2023). "The LIGHT trial (ClinicaL efficacy of Inhibition of orGan dysfunction througH bermekimab in systemic sclerosis: a proof-of-concept double-blind randomized clinical Trial) investigated the clinical efficacy of IL-1α inhibition in advanced SSc by bermekimab." (PMID 37680472, 2023).
chronic obstructive pulmonary disease (14 papers, 2011 to 2025). A chronic and progressive lung disorder characterized by the loss of elasticity of the bronchial tree and the air sacs, destruction of the air sacs wall, thickening of the bronchial wall, and mucous accumulation in the bronchial tree. "In the lung, IL-1α is associated with inflammation during lung injuries and diseases such as chronic obstructive pulmonary disease (COPD)." (PMID 35741013, 2022). "Clinically, the expression of IL-1α is reported to be greatly elevated in the lung tissues of chronic obstructive pulmonary disease (COPD) patients." (PMID 34375302, 2021). "Foamy macrophages contribute significantly to the chronic inflammatory milieu of chronic obstructive pulmonary disease (COPD) by releasing pro-inflammatory cytokines such as IL-6, TNF-α, IL-1α, and IL-1β." (PMID 41009372, 2025). "The proinflammatory cytokines interleukin (IL)-1α and IL-1β were significantly elevated in the lung-tissue and sputum samples of patients with chronic obstructive pulmonary disease who smoked compared to those of nonsmokers." (PMID 39335573, 2024). "In addition, IL-1α fragments of similar size to GrB processed fragments were detected in BALF from patients with cystic fibrosis, chronic obstructive pulmonary disease and bronchiectasis." (PMID 22479366, 2012). "In contrast, in patients with chronic obstructive pulmonary disease (COPD), a chronic inflammatory lung disease, both AIM2-mediated canonical and noncanonical inflammasomes participate the IL-1α-induced release of TGF-β in PBMCs." (PMID 37446052, 2023).